CEBPB (CCAAT enhancer binding protein beta)
Diseases named in the same sentence as CEBPB in open-access papers (continued):
Sharing a sentence is not in itself a finding about the gene and the disease.
tumor (continued). "In contrast, bile duct expression of CEBPB and FGFR2 were elevated in HB tumor regions as compared to the non-tumor regions." (PMID 36996081, 2023). "In contrast, the percentages of parenchymal cells that were immuno-positive for CEBPB or FGFR2 were not significantly different between CC and HB tumor and non-tumor livers." (PMID 36996081, 2023). "Consistent with its role in MMP gene expression, CEBPβ knockdown significantly reduced invasion, but not migration, of RCC tumor cells." (PMID 23342250, 2012). "Importantly, we found significant negative correlation between tumour SPARC with nuclear expression of the p65RelA, cJun, and cEBPβ in advanced stage (T3+) OvCa specimens in TMAs where only tumour cores are present." (PMID 30765860, 2019). "Since we demonstrated that IL-1β-induced collagen invasion of RCC cells was dependent on MMP enzymatic activity and that IL-1β-induced MMP expression was dependent on CEBPβ, we next asked whether or not CEBPβ was required for IL-1β-mediated RCC tumor cell invasion." (PMID 23342250, 2012).
cancer (238 papers, 2006 to 2026). A tumor composed of atypical neoplastic, often pleomorphic cells that invade other tissues. "Clusters 3 and 5 showed elevated expression of genes associated with cancer development and progression, such as CEBPB, PLIN2, PRDX1, PSMD6, and TXNRD1." (PMID 39805002, 2025). "ASNS, the gene encoding asparagine synthetase, has been reported as a direct target of ATF5 and CEBPB, and its over-expression is associated with cancer cell proliferation, metastasis and therapeutic resistance." (PMID 34065488, 2021). "Survival data curated from The Cancer Genome Atlas (TCGA) revealed that the expression of cEBPβ, cJun, cFos, and NFkB1 were associated with poor patients’ survival." (PMID 30765860, 2019). "Furthermore, this study revealed that PCD-regulated CEBPB-positive cancer-associated fibroblast (CAF) populations are a key determinant of the TNBC immune Microenvironment heterogeneity and poor prognosis." (PMID 40145099, 2025). "Besides, CDKN2C and ID2 are downregulated while IL6, BIRC3, PLAT, PPARG, and CEBPB are upregulated in three candidate TCM associated with Transcriptional misregulation in the cancer pathway." (PMID 34490085, 2021). "In addition to CTCF, we identified mutations in motifs of CEBPB across many cancer types and, in particular, mutations affecting the CpG site of the motif that were attributable to the SBS1 signature." (PMID 34282050, 2021). "Here, we characterized the in vitro and in vivo anti-cancer efficacy of novel synthetic cell-penetrating peptides (Bpep and Dpep) designed to interfere with the formation of active leucine-zipper-based dimers by CEBPB and CEBPD, transcription factors implicated in multiple malignancies." (PMID 34065488, 2021). "EGFR, a well-known driver of cell proliferation, was downregulated, aligning with the reduced proliferative capacity of cancer cells after CEBPB knockdown." (PMID 41411347, 2025). "Pre-CAFs exhibited a high expression of genes like PDGFRA, POSTN, BMP2, BMP5, CEBPB, and BICC1, associated with the serrated pathway of CRC and cancer progression." (PMID 39456726, 2024). "CCAAT enhancer binding protein beta (CEBPβ) binding to a CAAT box in the ALDH1A3 promoter is responsible for the overexpression of the ALDH1A3 gene in several cancer cells." (PMID 39001459, 2024). "Another study also revealed that saikosaponin D exerted anti-cancer effect against HCC by suppressing COX-2 via inhibiting p-STAT3/CCAAT enhancer binding protein beta (C/EBPβ) pathway." (PMID 39354529, 2024). "CEBPB was a well-studied transcription factor and had also been found to participate in cancer development." (PMID 38007473, 2023). "Radiotherapy is part of the standard of care for GBM and other cancers and significantly, ATF5, CEBPB and CEBPD have been associated with cancer cell radiation resistance." (PMID 36831248, 2023). "We examined the involvement of PP2A, Akt, and Nrf2 in the expression levels of CEBPB in cancer spheroid models." (PMID 37958656, 2023). "The activation of PP2A by FTY720-P reduced the expression levels of the CYP3A4 and CEBPB in cancer spheroid models." (PMID 37958656, 2023). "For example, there is evidence that CEBPB directly associates with bZIP protein ATF4, a key regulator of cellular responses to various types of stress that can either protect cancer cells or promote their demise, depending on circumstances." (PMID 36831248, 2023). "In consonance with past reports cited above in which interference with ATF5, CEBPB or CEBPD expression suppressed migration of cancer cells." (PMID 36831248, 2023). "We then investigated the effects of KCa1.1 inhibition with PAX on the expression levels of CEBPB transcripts in cancer spheroid models." (PMID 37958656, 2023). "The Akt/Nrf2/CEBPB axis was mainly involved in the induction of CYP3A4 by cancer spheroid formation, and the inactivation of Akt through the inhibition of KCa1.1 induced the down-regulation of CYP3A4, which is involved in DOX metabolism." (PMID 37958656, 2023).
cancer (continued). "SCNV gain was identified in several genes such as E2F1, ASPH, BLVRA, and CEBPB across multiple cancers." (PMID 37497116, 2023). "Abnormal over‐expression of CEBPB has been reported in many human cancers and is related to cancer progression and poor prognosis." (PMID 35726713, 2022). "Under stress conditions, such as cancer microenvironments, CEBPB is involved in BCR–ABL1 mediated myeloid expansion and leukemic stem cell exhaustion in the CML chronic-phase." (PMID 32471360, 2020). "We focused on CCAAT Enhancer Binding Protein-beta (C/EBP-β) because a number of reports have shown that it regulates the expression of various kinds of cytokines in immune as well as cancer cells." (PMID 26848978, 2016). "The binding of CEBPβ, a transcription factor shown to regulate cancer cell survival, to the promoter of BC041455 further suggests clinical significance of the target lncRNAs." (PMID 28003470, 2016). "Jun, CSF2 and IL-8 showed increased expression in IMR90 cells, whereas, NFκB1, NFκBIA, FN1 (fibronectin 1), GADD45A, BIRC2, TMEPAI (prostate androgen induced RNA) and CEBPB (CCAAT/enhancer binding protein) were up regulated in cancer cells." (PMID 22321936, 2012). "For example, CEBPB (NFIL6) is a principal effector of cyclin D1 activity in human cancer and an enhancer of e.g. IL-6 transcription, which plays an important role in the acute phase response." (PMID 21799770, 2011). "Moreover, CEBPB has been linked to the regulation of genes involved in the epithelial–mesenchymal transition (EMT), a process that is critical for cancer cell invasion and metastasis." (PMID 40226120, 2025). "Given its critical functions in other cancers, CEBPB may play a significant role in ccRCC pathogenesis and progression." (PMID 40949418, 2025). "The role of CEBPB and its isoforms in cancer is complex and context dependent." (PMID 40226120, 2025). "Active Nrf2 may be promoted by the Akt signaling pathway and up-regulate CEBPB, suggesting that the Akt-Nrf2 signaling pathway triggers the induction of CEBPB in cancer spheroid models." (PMID 37958656, 2023). "In GAC, CEBPB upregulation enhances the proliferative activity of cancer cells." (PMID 37874419, 2023). "CEBPB and Nrf2 cooperatively contributed to anti-cancer drug resistance." (PMID 37958656, 2023). "We tested whether the transcription factors that have been reported to induce PD-L1 in other cell or cancer types, including CEBPβ, NRF2 and RelB induced PD-L1." (PMID 37985999, 2023). "More interestingly, a higher expression of CEBPB could indicate a higher sorafenib resistance in 12 types of cancer in GDSC (liver hepatocellular carcinoma (LIHC), BRCA, CESC, COAD + READ, UCEC, STAD, MESO, PRAD, KICH + KIRC + KIRP, TGCT, THCA, and BLCA)." (PMID 38007473, 2023). "The findings suggest that the elevated expression of FGFR2 and CEBPB in liver may contribute to cancer development in CC patients." (PMID 36996081, 2023). "ALDH1A1 could regulate retinoid signaling via the CEBPB to promote stemness maintenance in cancer stem cells." (PMID 35280765, 2022). "The cancer cells enable stromal ones to up-regulate CCL20 thanks to the paracrine trigger of the molecular cascade by the activation of the transcription factor CCAAT enhancer binding protein beta (C/EBPβ) and to the release of IL6." (PMID 31096567, 2019). "In addition, seven inflammation‐related genes are shown to be regulated by the transcription factor CEBPB, which functions to both promote proliferation and arrest growth in different cell types and is itself frequently dysregulated in cancer." (PMID 28145099, 2017).
cancer (continued). "Validated miR-155 target genes are present in multiple pathways associated with cancer and cancer progression, including EMT (SMAD5), proliferation (SOCS1, INPP5D, and CSF1R), block of differentiation (SPI1, CEBPB), and apoptosis (CASP3, FADD, APAF1, and FOXO3A)." (PMID 27128908, 2016). "Consequently, CEBPB may play a pivotal role in the “inflammation-cancer” nexus by modulating the NF-κB/STAT3 signaling pathway." (PMID 40487290, 2025). "A higher CEBPB could also indicate a higher IC50 of sorafenib in patients with cancer." (PMID 38007473, 2023). "Our findings show that pre-treatment with Dpep, a cell-penetrating peptide designed to target the transcription factors ATF5, CEBPB, and CEBPD, sensitizes a variety of cultured cancer cells to the cytotoxic activity of NK-92MI cells." (PMID 40358191, 2025). "Several studies indicate that CEBPB and CEBPD promote metabolic reprogramming and affect glycolysis in various cancer cell types." (PMID 38920655, 2024). "The cell-penetrating ATF5/CEBPB/CEBPD inhibitor peptide Dpep upregulates TXNIP mRNA and protein in the majority of cancer cell lines surveyed." (PMID 38920655, 2024). "Bicluster 1 CpGs were found enriched in binding regions of TFs including GRHL2, TFAP2C, FOXA1, ER, CEBPB and NR5A2, TFs known to be important in many cancer‐related functions such as proliferation, stemness and epithelial‐to‐mesenchymal transition (EMT)." (PMID 38671580, 2024). "We, therefore, examined the involvement of JNK and ERK in the expression levels of CEBPB and CYP3A4 in cancer spheroid models." (PMID 37958656, 2023). "As will be discussed here, the leucine zippers of ATF5, CEBPB and CEBPD are key features in the design of cell-penetrating decoy peptides to target them for brain and other cancers." (PMID 36831248, 2023). "In this review, we relate how ATF5 and then CEBPB and CEBPD were identified as targets for treatment of brain and other cancers." (PMID 36831248, 2023). "As a transcription factor, CEBPB was reported to be translationally regulated by EIF6 and regulate the MAPK pathway in cancer." (PMID 35459206, 2022). "Important cancer-related molecules were observed as potential regulators for the DEPs, such as MYC, CD3, CEBPB, PI3K complex, SMARCA4 and the anti-cancer chemical drugs 5-fluorouracil, dexamethasone, sirolimus (rapamycin) and tretinoin." (PMID 33656060, 2021). "This prompted us to design and assess cell-penetrating dn decoy forms of CEBPB and CEBPD in the context of cancer treatment." (PMID 34065488, 2021). "The gene-regulatory factors ATF5, CEBPB and CEBPD promote survival, growth, metastasis and treatment resistance of a range of cancer cell types." (PMID 34065488, 2021). "CCAAT enhancer binding proteins (CEBPs) including CEBPA, CEBPB, CEBPD, CEBPE, CEBPG and CEBPZ, are suggested as potential biomarkers for cancer prognosis." (PMID 34743716, 2021). "Together, these findings indicate that Bpep/Dpep reduce expression of well-defined ATF5, CEBPB and CEBPD targets with cancer relevance." (PMID 34065488, 2021). "As an example, CEBPB forms functional heterodimers with ATF4, another transcription factor that protects cancer cells under stress conditions." (PMID 34065488, 2021). "The results indicated that CEBPB was expressed at higher levels in cancer tissues compared to adjacent non-cancerous tissues." (PMID 40949418, 2025). "In particular, H2AFV, CEBPB, SEC61G, GLRX, and PSMA5 exhibited dramatically worse overall survival in multiple cancers, which was consistent with their high expression in a variety of cancer tissues." (PMID 37251379, 2023).
cancer (continued). "It is anticipated that a better understanding of the proximal transcriptional events triggered by cell-penetrating peptides that target ATF5, CEBPB and CEBPD will better define their mechanisms of action, which in turn will inform their best use in therapies for treatment of brain and other cancers." (PMID 36831248, 2023). "Transcription factor (TF) motifs, including CEBPB (+), FOSB (+), SAP30 (+) and ATF4 (+), were significantly upregulated in CNV high cancer cells, while IRF3 (+), ETV7 (+), STAT1 (+) and IRF7 (+) were downregulated, indicating promising new regulatory networks driven by TFs in OS cells." (PMID 36596773, 2023). "ATF5, CEBPB and CEBPD have been reported to contribute to cancer cell radiation resistance." (PMID 34065488, 2021). "CEBPB, MEIS3, and TEAD4 were co-expressed with has-miR-5p in cancers." (PMID 32637580, 2020). "Apart from IL8, the co-regulation between NF-κB and AP1, CEBPB or STAT3 for genes IL1B, ICAM1, IL6, PTGS2, and SAA1 in the TF regulatory networks is consistent with previous observation in HNSCC or other cancer cells." (PMID 24069219, 2013). "Among them were CEBPA and CEBPB (cell cycle regulation), RELA and CREL (NF-κB pathway), TCF7L1 (Wnt/β-catenin signaling pathway), SMAD3 [transforming growth factor beta (TGF-β) signaling], FOXO1 and NFAT, all of which are involved in cancer initiation and progression." (PMID 28344555, 2017). "While this review focuses on ATF5, CEBPB and CEBPD in the context of brain cancers, it is important to consider, as we briefly do here, the roles of these transcription factors in other types of cancers and how the targeted peptide drugs discussed here may be used to treat these as well." (PMID 36831248, 2023). "Some factors identified (e.g., NF-κB, STAT3, FOS) are known to be involved for transformation in our model, others (e.g., CEBPB, HIF1a, ETS2, FHL2, TCF7L2, and NFE2L2) have been described as oncogenes in other settings, and some proteins (BHLHE40 and MAFB) have not been well linked to cancer." (PMID 29802342, 2018). "We have developed cell-penetrating peptides that target the transcription factors ATF5, CEBPB, and CEBPD and that promote apoptotic cancer cell death both in vitro and in vivo without apparent toxicity to non-transformed cells." (PMID 40358191, 2025). "We have designed cell-penetrating peptides that target the leucine zipper transcription factors ATF5, CEBPB and CEBPD and that promote apoptotic death of a wide range of cancer cell types, but not normal cells, in vitro and in vivo." (PMID 38920655, 2024). "There are many potential advantages of using combination treatments rather than monotherapies for cancer treatment, and findings thus far indicate that this is so for cell-penetrating ATF5, CEBPB and CEBPD decoy peptides." (PMID 36831248, 2023). "We see our results as a starting point for further experimental validation that will or will not show that the ability of CEBPB and E2F1-DP1 TF dimers to cooperatively bind to DNA upon methylation affects the NDUFA13 gene transcription and, potentially, lead to the onset of cancers." (PMID 37529293, 2022).
infection (55 papers, 2009 to 2025). The state of being infected such as from the introduction of a foreign agent such as serum, vaccine, antigenic substance or organism. "CEBPB, involved in monocyte development, is key in the response to many types of infection but occasionally cause immunopathology." (PMID 32872640, 2020). "Several genes such as CP, HP, and ORM1 are involved in the acute-phase response, indicating that a decrease in CEBPB can influence systemic responses to injury, infection, or other stress factors." (PMID 41002959, 2025). "Consistent with upregulation of CEBPB and hBD1 following H37Rv-infection, the binding of CEBPB to the DEFB1 promoter increased in H37Rv-infected AEC-II cells compared with in cells without infection." (PMID 38397085, 2024). "In order to elucidate the role of CEBPB in PRRSV infection, Marc-145 cells were transfected with si-CEBPB, followed by infection with PRRSV for 36 h." (PMID 38750508, 2024). "Also inhibited were CEBPB and insulin-related processes, likely contributing to the reduced acute phase response (inflammatory/infection) signaling." (PMID 34209203, 2021). "In addition, except for 4 of the regulatory genes (IRF4, JAK1, NFATC4 and STAT6), many of the other genes in this pathway were only transiently expressed at 2 (IL4R and PTPRC) or 4 and/or 8 (IL13, IL4 and CEBPB) weeks post-infection." (PMID 23448601, 2013). "This is inconsistent with the observed increase in CEBPB expression and its binding to the DEFB1 promoter after H37Rv infection." (PMID 38397085, 2024). "However, how H37Rv infection regulates the activity of CEBPB in AEC-II cells remains unknown." (PMID 38397085, 2024). "The systems biology analysis identified multiple immune system and inflammation molecules (e.g., STAT3, STAT1, CEBPB, JUN, IGF1, SPP1, NFKB2, IL-1β, and CSF1) as master regulators that are activated upon infection." (PMID 26865111, 2016). "To investigate whether the transcriptional activity of CEBPB on DEFB1 is regulated by the AMPK and mTOR pathways and the resulting truncation of CEBPB, we first examined the activation of AMPK and mTOR in AEC-II cells after H37Rv infection." (PMID 38397085, 2024). "In addition, we found that the protein expression level of CEBPα is significantly up-regulated 14 days post-infection and 21 days post-infection, while the CEBPβ expression level did not significantly change." (PMID 36747241, 2023). "However, in A549 cells, we found that binding of CEBPB to motif 1 and motif 2 in site 1 may have an inhibitory effect on DEFB1 transcription, as truncation of motif 1, motif 2, or motif 1+2 (site 1 as a whole) increased DEFB1 transcription after H37Rv infection." (PMID 38397085, 2024).
neurodegenerative disease (13 papers, 2014 to 2025). A disorder of the central nervous system characterized by gradual and progressive loss of neural tissue and neurologic function. "Recently, CEBPB has been reported as a potential neurodegenerative disease-related gene." (PMID 36139449, 2022). "Several evidences from our study demonstrated how the obesity driver CEBPB-LAP is promoting the mitochondrial Mon-gene-signature and how it is related to multiple neurodegenerative diseases and their biology at the cellular level." (PMID 41282072, 2025). "Among these transcription factors, the CCAAT enhancer-binding protein beta (CEBPB) and krupple like factor 4 (KLF4) have been documented previously in neurodegenerative diseases." (PMID 34720873, 2021). "Although CEBPB has not been reported in FTD per se, the interplay between microglia and neuroinflammation is a central process in all neurodegenerative diseases." (PMID 34720873, 2021).